MTOR (mechanistic target of rapamycin kinase)
Diseases named in the same sentence as MTOR in open-access papers (continued):
Sharing a sentence is not in itself a finding about the gene and the disease.
Pompe disease (3 papers, 2014 to 2018). "We have elucidated the molecular mechanisms underlying mTOR dysregulation in Pompe disease and identified points for therapeutic intervention along the mTOR signaling pathway." (PMID 28130275, 2017). "In this study, we have examined the involvement of the mTOR pathway in the pathophysiology of a severe muscle wasting condition, Pompe disease, caused by excessive accumulation of lysosomal glycogen." (PMID 28130275, 2017). "The information regarding mTOR signaling in Pompe muscle cells is limited to a recent finding of reduced insulin‐stimulated mTORC1 activation in two cellular models of Pompe disease—GAA‐knockdown C2C12 myoblasts and GAA‐deficient human fibroblasts from infantile Pompe patients." (PMID 28130275, 2017). "Recently, the dysregulation of the mammalian target of rapamycin (mTOR) signaling has been described in skeletal muscle in Pompe disease." (PMID 30382921, 2018). "It appears that AMPK‐TSC2 pathway is a much better therapeutic target in Pompe disease since the increased activity of these proteins and their excess at the lysosome are responsible for mTOR inhibition." (PMID 28130275, 2017). "To explore the mTOR signaling pathway in Pompe disease, we took advantage of a recently developed in vitro model of the disease—GAA‐deficient myotubes." (PMID 28130275, 2017). "Perhaps even more relevant to Pompe disease is the data indicating that the Rag family also signals glucose concentration to mTOR; in other words, glucose, like amino acids, controls mTORC1 recruitment to the lysosomal surface and its activation." (PMID 25183957, 2014). "Experiments in muscle cell culture and an animal model of Pompe disease demonstrate that the diseased muscle cells exhibit reduced mTOR activity, defective dephosphorylation of its key substrates, and inability to displace mTOR from lysosome upon nutrient deprivation." (PMID 28130275, 2017). "Thus, we have identified promising therapeutic targets to reverse aberrant mTOR signaling in Pompe disease." (PMID 28130275, 2017). "We, too, observed mTOR‐dependent inhibition of ULK1 in GAA‐KO muscle following TSC knockdown, but in the setting of Pompe disease, this suppression of autophagy turned out to be beneficial as shown by the removal of the autophagic buildup." (PMID 28130275, 2017). "An interesting parallel between Pompe disease and XMEA is that both are autophagic myopathies and both exhibit lysosomal acidification defect, but the molecular mechanism of mTOR dysregulation could not be more different." (PMID 28130275, 2017).
postpartum depression (3 papers, 2016 to 2024). A type of clinical depression that occurs after childbirth. "The findings suggested that resveratrol enhanced postpartum depression by increasing the activity of SIRT1 and autophagy indicators, reducing the p62 protein expression, and suppressing the activation of AKT and mTOR via inhibition in the hippocampus." (PMID 39494329, 2024). "Resveratrol can potentially reduce postpartum depression in mice by activating SIRT1, enhancing autophagy, and suppressing the mTOR pathway." (PMID 39494329, 2024). "In the current study, we found for the first time that the phosphorylation of Akt and mTOR as well as the expression of GluR1 decreased in PFC of OB mice, consistent with the results in the chronic mild stress model and the postpartum depression model." (PMID 30687098, 2018). "Mice that experienced chronic prepregnancy stress became vulnerable to postpartum depression, and also exhibited not only an abnormal GluR1/NR1 expression ratio but also a deficit in Akt/mTOR signaling." (PMID 27756905, 2016).
prostatic intraepithelial neoplasia (3 papers, 2006 to 2012). "Furthermore, suppression of mTOR by rapamycin effectively reverses AKT-dependent prostatic intraepithelial neoplasia (PIN) in mouse model studies." (PMID 22567414, 2012).
psoriasis vulgaris (3 papers, 2015 to 2021). Plaque psoriasis is the most common presentation of psoriasis. "Immunosuppressant methotrexate (MTX) had been widely used in the treatment of psoriasis vulgaris, which returned to the normal function of peripheral blood regulatory T cells in plaque psoriasis via the AMPK/CD73/mTOR pathway." (PMID 34512732, 2021). "Thus far, efforts to inhibit mTOR-associated pathways (e.g., rapamycin) have achieved only limited efficacy for treatment of plaque psoriasis, although some efficacious topical agents are known to inhibit AKT/mTOR signaling." (PMID 26251673, 2015).
respiratory failure (3 papers, 2022 to 2025). The significant impairment of gas exchange within the lungs resulting in hypoxia, hypercarbia, or both, to the extent that organ tissue perfusion is severely compromised. "Intriguingly, this is comparable to a human age of approximately 40–50 years, the average age of respiratory failure in patients with LAM requiring initiation of the allosteric mTOR inhibitor rapamycin (sirolimus)." (PMID 38127441, 2023).
rheumatic diseases (3 papers, 2022 to 2025). "In conclusion, the mTOR signalling pathway is the primary connection between MetS and rheumatic disorders, and MetS may be a significant risk factor for rheumatic conditions like RA, AS and GO." (PMID 39789419, 2025). "These genes have a significant impact on the pathophysiology of numerous rheumatic diseases, particularly by regulating the mTOR pathway and immunometabolism signalling." (PMID 39789419, 2025). "The chronic state of mTOR activation exacerbates the clinical signs of rheumatic diseases by generating pro‐inflammatory necrosis and the depletion of metabolic resources." (PMID 39789419, 2025). "Mammalian target of rapamycin (mTOR) can facilitate B‐cell activation and autoantibody production, and the clinical efficacy of rapamycin in the treatment of rheumatism has been proved." (PMID 35875970, 2022). "Therefore, research integrating these recently identified genes with the mTOR pathway advances our knowledge of the pathophysiology of rheumatic disorders and offers fresh concepts for mTOR signalling‐based targeted therapy." (PMID 39789419, 2025). "For example, IL-37, a member of the IL-1 family which is stimulated by SARS-CoV-2, has been shown to suppress IL-1β, IL-6, TNFα and CCL2 in rheumatic diseases by acting on mTOR and enhancing the AMPK activity, to maintain mitochondrial membrane potential and limit the toxic effects of ROS." (PMID 36389723, 2022).
Roberts syndrome (3 papers, 2013 to 2023). "Our work suggests that stimulation of the mTOR pathway with the amino acid L-leucine has therapeutic potential for Roberts syndrome." (PMID 24098154, 2013). "Leucine supplementation has been previously proposed as a therapeutic approach in other genetic disorders, including Roberts syndrome and Diamond-Blackfan anemia, that are also characterized by dysregulation of mTOR signaling, protein translation and autophagy." (PMID 37934770, 2023). "In addition, our work suggests that some of the differential gene expression in Roberts syndrome may be explained by translational inhibition connected with the inhibition of the mTOR pathway." (PMID 24098154, 2013).
serous carcinomas (3 papers, 2018 to 2023). "In contrast, in serous carcinomas, increased mTOR phosphorylation levels were more commonly found in advanced stages of disease." (PMID 32961868, 2020). "Immunohistochemical analyses of PI3K/AKT/mTOR have shown that this pathway is activated in roughly half of all cases of high-grade serous adenocarcinoma (SAC) of the ovary." (PMID 29844867, 2018).
sickle cell disease (3 papers, 2022 to 2023). Sickle cell anemias are chronic hemolytic diseases that may induce three types of acute accidents: severe anemia, severe bacterial infections, and ischemic vasoocclusive accidents (VOA) caused by sickle-shaped red blood cells obstructing small blood vessels and capillaries. "The employment of mTOR inhibitors for the treatment of β-thalassemia and sickle-cell diseases is supported by several laboratory investigations, pre-clinical studies, and clinical data." (PMID 37894732, 2023). "The mTOR (mammalian Target of Rapamycin) inhibitor rapamycin (RAPA) is of great interest as a possible re-positioned drug for β-thalassemia and sickle-cell disease (SCD), as it is already used in patients undergoing kidney transplantation." (PMID 36614221, 2023).
skin rashes (3 papers, 2014 to 2025). "Additionally, isotretinoin was also recommended in the management of other types of skin rashes induced by oncologic medications, such as epidermal growth factor inhibitors, BRAF inhibitors, MEK inhibitors, and mTOR inhibitors." (PMID 39963639, 2025).
skin squamous cell carcinoma (3 papers, 2017 to 2023). A carcinoma arising from the squamous cells of the epidermis. "Curcumin administered by oral gavage in immunodeficient mice significantly inhibited skin squamous cell carcinoma (SCC) growth and downregulated pS6, a well-established downstream biomarker of the mammalian target of rapamycin (mTOR) and MEK/ERK pathways." (PMID 29565284, 2018).
squamous intraepithelial lesions (3 papers, 2014 to 2020). "Immunohistochemical analysis of the mTOR pathway markers phosphorylated-mTOR (p-mTOR), p-p70S6K, and EGFR revealed a highly positive expression in high grade squamous intraepithelial lesions (HSIL) and all SCC stains." (PMID 31947591, 2020). "In addition, the mTOR pathway is important in cervical carcinogenesis and thus, targeted therapies may be developed for SCC as well as its precursor lesion, high-grade squamous intraepithelial lesion." (PMID 25202355, 2014).
staphylococcus aureus infection (3 papers, 2020 to 2026). An infectious process in which the bacteria Staphylococcus aureus is present. "KEGG pathway analysis demonstrated that genes were mainly enriched in staphylococcus aureus infection, MAPK signaling pathway, and mTOR signaling pathway." (PMID 33553270, 2020). "Furthermore, the KEGG pathway analysis suggested that DEGs were mainly enriched in staphylococcus aureus infection, MAPK signaling pathway, mTOR signaling pathway, calcium signaling pathway, and complement and coagulation cascades." (PMID 33553270, 2020).
stenosis (3 papers, 2021 to 2024). "We found that the pharmacological inhibition of mTOR (with rapamycin) can prevent SMC migration and arterial stenosis in the CAWS model of KD." (PMID 39271773, 2024). "Plumbagin can attenuate rat tracheal stenosis via TGF-β1/Smad and Akt/mTOR signaling." (PMID 34304701, 2021). "We hypothesized that plumbagin attenuated rat tracheal stenosis after injury by regulating the activation of fibroblast through TGF-β1/Smad and Akt/mTOR signaling pathway." (PMID 34304701, 2021).
synovitis (3 papers, 2013 to 2025). Inflammation of a synovial membrane. "This suggests a complex interaction between the underlying iMCD and RA-like synovitis, highlighting the pivotal role of mTOR in the pathogenesis of joint destruction." (PMID 40589696, 2025). "The association of synovitis with night pain in the “High mTOR” group and pain on walking and standing in the “Low mTOR”set requires much studying to better understand these differences." (PMID 23864948, 2013). "Increases in the expression of mTOR in PBMCs of OA patients are related to disease activity, being associated with synovitis more than with pain." (PMID 23864948, 2013). "Therefore, upregulation of mTOR gene expression might indicate the type of the OA disease activity associated with advanced cartilage destruction and synovitis." (PMID 23864948, 2013). "Increased expression of mTOR in PBMCs of OA patients is related to the presence of synovitis and is seen in all patients requiring joint replacement." (PMID 23864948, 2013). "These “Low mTOR” subset subjects experienced significantly more pain upon walking, and standing and increased total joint stiffness versus “High mTOR” subset, while the latter more often exhibited synovitis." (PMID 23864948, 2013).
testicular tumors (3 papers, 2019 to 2025). "Gonadotropin-releasing hormone treatment may protect against testicular tumor development by downregulating oncogenes, such as MALAT1, mTOR, C-MYC, and EZH2 to enable normal germ cell development." (PMID 31890219, 2019).
thrombotic microangiopathy (3 papers, 2021 to 2025). The syndromes of microangiopathic hemolytic anemia, thrombocytopenia, and variable signs of organ impairment, due to platelet aggregation in the microcirculation. "mTor inhibitor without CNI (1%) was used in only one patient due to CNI induced thrombotic microangiopathy." (PMID 33939755, 2021).
thymic epithelial tumors (3 papers, 2019 to 2023). "Several phase I/ II studies of mTOR inhibitors were reported in advanced thymic epithelial tumors, reporting on high disease control rates." (PMID 30897085, 2019).
thymic lymphoma (3 papers, 2012 to 2022). "Here we used transcript profiling of radiation induced thymic lymphomas to investigate the molecular signaling pathways that contribute to tumorigenesis in Fbxw7 heterozygous mice and their dependence on mTOR." (PMID 26575021, 2015).
urinary tract infection (3 papers, 2019 to 2022). "Urinary tract infections caused by polyomavirus or CMV were even less frequently observed in 4930 renal transplant recipients receiving mTOR inhibitors as compared with those treated with mycophenolate for preventing graft rejection." (PMID 30700842, 2019).
uveitis (3 papers, 2018 to 2021). An inflammatory process affecting a part of or the entire uvea. "mTOR inhibition was found to be effective in the treatment of uveitis – intraocular inflammatory condition – uveitis, as well as in experimental models of various eye diseases with neovascular component, suggesting that mTOR is a prospective target for the treatment of CNV." (PMID 31200728, 2019). "Consequently, this review will clarify the available evidence for ophthalmologists and clinical decision makers regarding the potential role of mTOR inhibition in uveitis treatment protocols, in terms of agent efficacy, adverse event rates and the capability for corticosteroid dose reduction." (PMID 29885659, 2018). "It has also been reported that the use of this mTOR inhibitor was safe and effective in treating non-infectious uveitis." (PMID 33957967, 2021). "The findings of this systematic review will help inform ophthalmologists and aid the improvement of treatment protocols for non-infectious uveitis with regard to the use of mTOR inhibitors." (PMID 29885659, 2018).
Venous thrombosis (3 papers, 2020 to 2025). Formation of a blood clot (thrombus) inside a vein, causing the obstruction of blood flow. "As the patient was highly sensitized and had a thrombosis of arteriovenous fistula, mTOR inhibitors were not recommended." (PMID 40761768, 2025).
Vestibular schwannoma (3 papers, 2020 to 2025). A vestibular schwannoma (also known as acoustic neuroma, acoustic neurinoma, or acoustic neurilemoma) is a benign, usually slow-growing tumor that develops from the VIIIth cranial nerve supplying the inner ear. "Similarly, targeted drugs for vestibular schwannomas, such as mTOR inhibitors, have achieved remarkable results in preclinical studies." (PMID 41459564, 2025).
vulvar cancer (3 papers, 2016 to 2025). "In vulvar cancer, mTOR is frequently expressed and identified as a downstream effector of the AKT pathway." (PMID 40647429, 2025). "For instance, dactolisib, a dual anti-PIK3CA/mTOR inhibitor, exhibited promising antitumor efficacy in an in vitro model for vulvar cancer by counteracting epithelial-to-mesenchymal transition." (PMID 38397025, 2024). "In vitro studies demonstrate that mTOR inhibitors such as rapamycin, everolimus, and AZD2014 effectively suppress the proliferation of vulvar cancer cell lines." (PMID 40647429, 2025).
Zinc deficiency (3 papers, 2022 to 2025). A deficiency of the essential metal Zinc; an essential cofactor for many enzymes. "The phosphorylated levels of PI3K, AKT, and mTOR were also significantly reduced, indicating that zinc supplementation effectively inhibits the activated PI3K/AKT/mTOR signaling pathway in zinc deficiency." (PMID 39028478, 2025). "Since PI3K/AKT/mTOR plays a vital role in autophagy regulation during follicle development, we examine the impact of zinc deficiency on this pathway." (PMID 38807213, 2024). "Thus, our data indicated that zinc deficiency inhibits autophagy by activating the PI3K/AKT/mTOR signaling pathway." (PMID 38807213, 2024). "This activation was accompanied by increased phosphorylation of mTOR, suggesting that inhibiting the PI3K/AKT/mTOR axis may be a critical way to rescue zinc deficiency-induced inhibition of autophagy." (PMID 38807213, 2024). "A decrease in mTOR protein levels due to zinc deficiency may also occur through this mechanism." (PMID 35955944, 2022). "In the context of zinc deficiency, this study has confirmed the significant activation of the TGF-β1/PI3K/AKT/mTOR signaling pathway." (PMID 39028478, 2025). "Both qPCR and WB results demonstrated that zinc deficiency significantly upregulated the mRNA and protein expression levels of TGF-β1, PI3K, AKT, and mTOR, as well as p-AKT, p-PI3K, and p-mTOR compared to the control group." (PMID 39028478, 2025). "Follow-up studies will elucidate the significance of the zinc deficiency-induced decrease in SIRT1 and mTOR protein levels on neuronal function." (PMID 35955944, 2022). "Additionally, we observed activation of the non-canonical TGF-β1 pathway PI3K/AKT/mTOR under zinc deficiency, which is known to regulate cell survival, proliferation, and fibrosis processes." (PMID 39028478, 2025). "However, no studies have investigated how zinc deficiency affects hippocampal neuronal autophagy and the important autophagy regulators, mTOR, and AMPK signaling." (PMID 35955944, 2022).
abortion (2 papers, 2023 to 2024). the ending of pregnancy by removing a fetus or embryo before it can survive outside the uterus. "A recent study conducted on a mouse model of abortion has shown that CaMK4 is essential for the regulation of Th17 cell infiltration and associated cytokine production at the maternal–fetal interface through the AKT/mTOR pathway." (PMID 39051375, 2024). "ICA may increase Treg cell expansion and reducing pro-inflammatory factors expression via the mTOR pathway, then reducing placental inflammation and improving pregnancy outcomes in abortion-prone mice." (PMID 36890410, 2023).
acute monocytic leukemia (2 papers, 2021 to 2025). Acute monoblastic leukemia (AML-M5), is one of the most common subtypes of acute myeloid leukemia (AML) that is either comprised of more than 80% of monoblasts (AML-M5a) or 30-80% monoblasts with (pro)monocytic differentiation (AML-M5b). "Tan-IIA has also been reported to induce apoptosis and autophagy in acute monocytic leukemia by inhibiting the PI3K/Akt/mTOR signaling pathway." (PMID 34588580, 2021). "The findings suggest that R. tripartita extracts induce cell cycle arrest and apoptosis via the PI3K/AKT/mTOR signaling pathway by reducing phosphorylation of mTORC1 substrate S6Ser2040‐244 and mTORC2 downstream target AKT‐Ser473 in acute monocytic leukemia THP‐1 cells." (PMID 40717210, 2025).
adenoid cystic carcinoma (2 papers, 2021 to 2024). A malignant tumor arising from the epithelial cells. "Isoliquiritigenin inhibits tumor angiogenesis in adenoid cystic carcinoma (ACC) cells through the obstruction of mTOR-dependent VEGF expression." (PMID 38611849, 2024).